LINC00470 (long independently transcribed non-coding RNA 470)
Diseases named in the same sentence as LINC00470 in open-access papers (continued):
Sharing a sentence is not in itself a finding about the gene and the disease.
astrocytoma (3 papers, 2018 to 2020). "The multivariate cox proportional hazards model indicated that LINC00470 expression and astrocytoma grades were independently associated with overall survival (hazard ratio [HR] = 2.876, P = 0.02; HR = 1.892, P = 0.044; respectively)." (PMID 29866190, 2018). "High LINC00470 expression was significantly associated with a poor prognosis of astrocytoma patients." (PMID 29866190, 2018). "LINC00470 levels, astrocytoma grade, age, and tumor site were associated with OS." (PMID 33634032, 2020). "Kaplan-Meier analysis of the 75 patients with astrocytoma revealed that high LINC00470 expression levels significantly correlated with shorter survival times." (PMID 29866190, 2018). "Our previous data demonstrated that LINC00470 expression levels in astrocytoma were significantly higher than those in normal brain tissues." (PMID 29866190, 2018). "We next measured LINC00470 levels in a panel of 75 astrocytoma tissues and 15 normal brain tissues by in situ hybridization." (PMID 29866190, 2018). "Finally, we confirmed the prognostic value of LINC00470 and that the high level expression of LINC00470 was an unfavorable prognosis marker for astrocytoma patients." (PMID 29866190, 2018). "To further evaluate the clinical significance of LINC00470 in astrocytomas, including GBMs, we found that the levels of LINC00470 were significantly increased in astrocytoma tissues (n = 60) compared with normal brain tissues (n = 12) by RT-qPCR, especially in high-grade astrocytomas." (PMID 29866190, 2018). "Subsequently, we conducted a univariate cox regression analysis using clinical variables for astrocytoma patients and found that expression of LINC00470, astrocytoma grade, patients’ age, and the astrocytoma location were statistically associated with overall survival." (PMID 29866190, 2018).
chronic myelocytic leukaemia (2 papers, 2021 to 2023). "LINC00470 acted as oncogene to inhibit autophagy and facilitate chemoresistance in chronic myeloid leukemia." (PMID 36987665, 2023).
endometrial cancer (2 papers, 2021 to 2022). Primary or metastatic malignant neoplasm involving the endometrium (mucous membrane that lines the endometrial cavity). "In addition, LINC00470 promoted invasiveness, migration, and angiogenesis of endometrial cancer cells." (PMID 35578166, 2022).
hepatocellular carcinoma (2 papers, 2021 to 2022). A malignant tumor that arises from hepatocytes. "Furthermore, LINC00470 can promote malignant behaviors of hepatocellular carcinoma cells, supporting the oncogenic effect of LINC00470 in cancers." (PMID 34249684, 2021).
melanoma (2 papers, 2021 to 2022). A malignant, usually aggressive tumor composed of atypical, neoplastic melanocytes. "The highly expressed LINC00470 was associated with the proliferation and migration ability of advanced melanoma cells, resulting in a rapid tumor growth rate in vivo." (PMID 33875645, 2021). "We discovered that LINC00470 was overexpressed in melanoma tissues and cells compared with the adjacent normal tissues and cells by qPCR." (PMID 33875645, 2021). "Knockdown of LINC00470 significantly suppressed the melanoma cell proliferation and migration, as well as the tumor growth in vivo." (PMID 33875645, 2021). "The detailed investigation about the molecular mechanisms indicated that LINC00470 promoted the proliferation and migration of melanoma cells by facilitating the APEX1 via regulating ZNF131." (PMID 33875645, 2021). "In the current study, we identified that LINC00470 was significantly upregulated in melanoma cells and tissues compared with the normal cells and tissues." (PMID 33875645, 2021). "Meanwhile, we detected LINC00470 expression in 20 paired melanoma tissue and adjacent normal tissue by qRT-PCR, and the expression of LINC00470 was significantly higher in melanoma tissues." (PMID 33875645, 2021). "Herein, we found that LINC00470 promoted the proliferation and migration of melanoma cells by facilitating the expression of APEX1." (PMID 33875645, 2021). "OE LINC00470 inhibited while knockdown LINC00470 promoted the mRNA expression level of APEX1 in melanoma cells." (PMID 33875645, 2021). "Knockdown of LINC00470 could significantly inhibit the melanoma cell proliferation and migration, and suppress the growth of tumor in vivo." (PMID 35578166, 2022). "The mechanism of LINC00470 in regulating the proliferation and migration in melanoma is still unknown." (PMID 33875645, 2021). "In contrast, the protein level of APEX1 was upregulated in melanoma tissues, indicating that other regulatory mechanisms to the target gene may exist except the LINC00470/ZNF131/APEX1 axis." (PMID 33875645, 2021). "Taken together, these results demonstrated that the LINC00470 was upregulated in melanoma tissues and cells, which might be used as a melanoma prognostic marker." (PMID 33875645, 2021). "Overall, these results demonstrated that LINC00470 could promote melanoma tumor growth through regulating APEX1." (PMID 33875645, 2021). "In addition, LINC00470 expression was upregulated in three melanoma cells (A375, SK-MEL-1, and SK-MEL-5), compared with the human normal skin melanocytes cell line PIG1." (PMID 33875645, 2021). "Interestingly, the protein expression level of APEX1 was increased when the melanoma cells were overexpressed LINC00470 and decreased when LINC00470 was knockdown." (PMID 33875645, 2021). "Therefore, we aimed to investigate the role of LINC00470 in the development of melanoma in this work." (PMID 33875645, 2021). "The overexpression of LINC00470 promoted the proliferation and migration of melanoma cells." (PMID 33875645, 2021). "In summary, our study demonstrated that LINC00470 could serve as a promising potential therapeutic target for melanoma patients." (PMID 33875645, 2021). "In contrast, knockdown of LINC00470 could significantly inhibit the melanoma cell proliferation and migration, and suppress the growth of tumor in vivo." (PMID 33875645, 2021). "Overexpression of APEX1 could reverse the impact of the silence of LINC00470 in melanoma cells." (PMID 33875645, 2021). "Moreover, overexpressing LINC00470 significantly increased melanoma cell migration." (PMID 33875645, 2021). "However, the underlying mechanism and the interaction between APEX1 and LINC00470 in melanoma are not clear." (PMID 33875645, 2021). "Therefore, we believe that LINC00470 may be used as a potential therapeutic target of melanoma." (PMID 33875645, 2021).
melanoma (continued). "In the present study, we revealed that LINC00470 was regulating APEX1 to promote the proliferation and migration of melanoma cells, resulting in significant tumor growth." (PMID 33875645, 2021). "All these results demonstrated that LINC00470 promoted cell proliferation and migration partly by enhancing the protein expression of APEX1 in melanoma cells." (PMID 33875645, 2021). "However, the functions and molecular mechanisms of LINC00470 remain unclear in melanoma." (PMID 33875645, 2021). "In summary, our studies revealed that LINC00470 promoted melanoma proliferation and migration by enhancing the expression of APEX1, which indicated that LINC00470 might be a therapeutic target for the treatment of melanoma." (PMID 33875645, 2021).
lung carcinoma (1 paper, 2020). "Result revealed a 6 lncRNA signal, including LINC01287, SNAP25-AS1, LINC00470, AC104809.2, LINC00645 and LINC01010, as an independent prognostic factor for predicting OS in lung cancer patients." (PMID 32518519, 2020). "We then identified a 6 lncRNA signature (LINC01287, SNAP25-AS1, LINC00470, AC104809.2, LINC00645 and LINC01010) that had the greatest prognostic value for lung cancer." (PMID 32518519, 2020).
tumor (10 papers, 2018 to 2024). "Tumor tissues were collected from each mouse, and the expression of LINC00470 in tumor tissues was determined by RT-qPCR." (PMID 34249684, 2021). "The results showed that, compared with the sh-NC, the expression of LINC00470 in tumor tissues was decreased in response to sh-LINC00470." (PMID 34249684, 2021). "In summary, LINC00470 up‐regulated the expression of MYC by sponging miR‐134 to exert a tumour‐promoting effect, while miR‐134 affected the expression of ABCC1 by targeting MYC." (PMID 32916774, 2020). "In addition, the repressive effects of temozolomide treatment on Ki67 and VEGF expression in tumor tissues were partially rescued by the overexpression of LINC00470 or SOX4." (PMID 36987665, 2023). "LINC00470 knockdown reduced tumor volume and growth rate, which could be reversed by knockdown of PTEN." (PMID 34249684, 2021). "Silencing LINC00470 significantly suppressed the growth of the tumor." (PMID 33875645, 2021). "Then, our IHC results exhibited that depletion of LINC00470 significantly increased the expression of PTEN in tumor tissues but reduced the microvessel density, which could be recovered by down-regulating PTEN." (PMID 34249684, 2021). "Besides, the growth rate and weight of tumors as well as microvessel density in the tumor tissues were significantly reduced after LINC00470 knockdown." (PMID 34249684, 2021). "Thus, we further examined the role of LINC00470 in tumor vascularization." (PMID 34249684, 2021). "Overexpression of LINC00470 or SOX4 partially abolished the suppressive effect of temozolomide and conspicuously elevated tumor volume and weight in nude mice in the presence of temozolomide." (PMID 36987665, 2023). "LINC00470 can also enhance the activity of AKT while inhibiting the ubiquitination of HK1, thereby inhibiting the autophagy of tumour cells while promoting tumorigenesis." (PMID 33749070, 2021). "H&E staining for the tumor tissues of nude mice revealed that cells in the GBM-exo group arranged more densely and had increased cell size when compared to the HC-exo group or sh-LINC00470-GBM-exo group." (PMID 33663509, 2021).
cancer (4 papers, 2021 to 2024). A tumor composed of atypical neoplastic, often pleomorphic cells that invade other tissues. "The potential for participation in cancer-associated processes decreases in a set of LINC00667, LINC00668 > LINC00470 > LINC01926, LINC01544, LINC01909, depending on the number of functional terms." (PMID 38540157, 2024). "The more cancer-specific lincRNAs are LINC00470, LINC00668, LINC00907, LINC01254, LINC01415, LINC01478, and LINC01539." (PMID 38540157, 2024). "In fact, LINC00470 has been reported to be an oncogene in other malignant tumors." (PMID 35578166, 2022).
infection (1 paper, 2021). The state of being infected such as from the introduction of a foreign agent such as serum, vaccine, antigenic substance or organism. "Further, RT-qPCR results showed that treatment with sh-LINC00470-1 and sh-LINC00470-2 reduced the expression of LINC00470 in KLE cells, and treatment with oe-LINC00470 enhanced the expression of LINC00470 in HEC-1-B cells, which validated the successful infection of LINC00470." (PMID 34249684, 2021).
LINC00470 also shares sentences with these, for which no sentence is quoted: acute myeloid leukemia (1 paper); in sarcoma (1); testicular germ cell tumor (1); thyroid cancer (1).